MIR4728 (microRNA 4728)
Synonyms: hsa-mir-4728
Gene: MicroRNA gene on chromosome 17 (39,726,495 to 39,726,561, forward strand). Ensembl gene ENSG00000265178.
Homologues: Orthologues: chimpanzee MIR4728 (100% identical).
Diseases named in the same sentence as MIR4728 in open-access papers:
MIR4728 is named in the same sentence as 1 disease in open-access papers, as found by Europe PMC text mining. Sharing a sentence is not in itself a finding about the gene and the disease.
MIR4728 shares sentences with these, for which no sentence is quoted: breast carcinoma (1 paper).